VCAM1 (vascular cell adhesion molecule 1)
Diseases named in the same sentence as VCAM1 in open-access papers (continued):
Sharing a sentence is not in itself a finding about the gene and the disease.
tuberculosis (3 papers, 1996 to 2020). A chronic, recurrent infection caused by the bacterium Mycobacterium tuberculosis. "Serum levels of s.ICAM-1 and s.VCAM-1 in patients with tuberculosis were higher than those in healthy controls (p < 0.001)." (PMID 18475740, 1996). "Concentrations of vWF and VCAM-1 were higher in mycobacteremic patients than in patients with HIV-tuberculosis without mycobacteremia, whereas concentrations of ADAMTS-13, Ang-1, and Tie-1 were lower." (PMID 28363198, 2017).
uremia (3 papers, 2015 to 2026). A clinical syndrome associated with the retention of renal waste products or uremic toxins in the blood. "This study shows that, in the presence of both traditional and uremia-related risk factors, VCAM-1 production in the IEA may be a marker for the development of more severe atheromatous lesions and a higher c-IMT in unselected KT candidates." (PMID 26066045, 2015). "Repeated bursts of such power activate endothelial NADPH-oxidase and NF-κB, up-regulating ICAM-1, VCAM-1, and pro-inflammatory cytokines; in uremia this cascade is amplified, further weakening the blood–brain barrier and permitting neurotoxic proteins and immune cells to invade the parenchyma." (PMID 41224909, 2026). "Plasma cytokine levels may vary greatly under certain uremia-related clinical conditions while soluble cellular adhesion molecules, particularly VCAM-1, have been found to be markers of post-transplant mortality." (PMID 26066045, 2015). "Thus paving the way also to the other newer FXa inhibitor, which recently demonstrated to affect VCAM-1 and ICAM-1 in uremia induced vascular dysfunction." (PMID 33301454, 2020).
age (2 papers, 2022 to 2025). A temporal measurement of the time period elapsed since an identifiable point in the life cycle of an organism. "In light of this, we found Smyd2 knockdown or heterozygous knockout mice ameliorates endothelial inflammation (iNOS, VCAM-1 and COX-2) upon Ang II infusion in vivo, which revealed that targeting Smyd2 possibly unveiled a novel therapeutic candidate of age-related endothelial inflammation." (PMID 36585926, 2022).
alpha-synucleinopathy (2 papers, 2024). "Finally, in order to overcome interference of non-AD copathology on BBM interpretation, VCAM1/ICAM1 and alpha-synuclein are emerging in research as new BBMs suitable for the identification and characterization of non-AD copathology such as vascular pathology and alpha-synucleinopathy, respectively." (PMID 39684623, 2024).
amyloid (2 papers, 2020 to 2025). "Increased numbers of infiltrating T cells were observed in amyloid-burdened brain regions of AD transgenic mice with concomitant up-regulation of endothelial adhesion molecules ICAM-1 and vascular cell adhesion molecule-1 (VCAM-1) compared to non-transgenic littermates." (PMID 32503641, 2020).
aplastic anaemia (2 papers, 2018 to 2020). "Furthermore, VCAM-1 is expressed at lower levels in some diseases characterized with mesenchymal stem cell deficiency or dysfunction, such as aplastic anemia." (PMID 29789783, 2018). "As a major adhesion protein, vascular cell adhesion molecule 1 (VCAM-1) has been found to be expressed at lower levels in some diseases that are characterized by a deficiency or dysfunction in mesenchymal stem cells, such as aplastic anemia." (PMID 29789783, 2018).
Ascites (2 papers, 2014 to 2025). Accumulation of fluid in the peritoneal cavity (between the layers of the peritoneum that lines the abdomen). "We therefore evaluated the association of VCAM-1 concentrations in serum and ascites with patient outcome." (PMID 25177246, 2014). "In ascites, low VCAM-1 and ICAM1- levels showed an association with surgeries exceeding 336 minutes whereas only VCAM1 has significant association." (PMID 40652770, 2025).
atopic dermatitis (2 papers, 2020 to 2023). "E-selectin, ICAM-1 (intercellular adhesion molecule-1), and VCAM-1 (vascular cell adhesion molecule-1) play a role in atopic dermatitis (AD)." (PMID 37109462, 2023).
bipolar depression (2 papers, 2023 to 2024). "Studies report contrasting results on imbalances in adhesion molecules, such as ICAM-1 and VCAM-1, in patients with both bipolar disorder and MDD, with the majority of them indicating a potential link between immune dysregulation and the development and progression of these conditions." (PMID 39056795, 2024).
bone cancer (2 papers, 2022 to 2024). A primary or metastatic malignant neoplasm affecting the bone or articular cartilage. "Circulating DC readily migrate to the bone marrow due to the high expression of vascular cell adhesion molecule-1 (VCAM-1) and endothelial selectin in the microvasculature of the bone marrow, which is critical for metastatic bone cancers." (PMID 38464516, 2024).
brain tumor (2 papers, 2022 to 2023). "This work illustrates the potential of VCAM-1–targeted MRI for improved delineation of the tumor-brain interface in both primary and secondary brain tumors." (PMID 35312755, 2022). "Together, these preclinical and clinical data suggest that VCAM-1–targeted MRI has the potential to augment existing MRI techniques, by exploiting microenvironmental changes at the periphery of brain tumors for greater accuracy of margin delineation, despite an undisrupted BBB." (PMID 35312755, 2022). "The spatial correspondence of VCAM-1 upregulation and the VCAM-MPIO–induced hypointensities was further confirmed in both the brain metastasis model and an orthotopic model of medulloblastoma, supporting the broader applicability of this concept across multiple brain tumor types." (PMID 35312755, 2022).
cerebral aneurysm (2 papers, 2014 to 2020). "We have previously found that TNF-α can activate a number of pro-inflammatory and matrix remodeling genes in cerebral vascular smooth muscle cells directly implicated in cerebral aneurysm formation, including: MMP-3, MMP-9, MCP-1, VCAM-1, and IL-1β; and IL-1β, VCAM-1 and MCP-1." (PMID 24739142, 2014).
chronic asthma (2 papers, 2013 to 2022). An asthma that is characterized by the development of persistent airway inflammation and recurrent attacks of breathlessness and wheezing, which vary in severity and frequency. "In addition, we observed reduced expression of VCAM-1 in mice treated with human anti-VCAM-1 mAb in both the acute and chronic asthma models." (PMID 23855490, 2013). "Furthermore, we observed anti-inflammatory effects for IV treatment of human anti-VCAM-1 mAb in acute and chronic asthma mouse models, as well as an anti-fibrosis effect in chronic asthma mice." (PMID 23855490, 2013). "Furthermore, mice with chronic asthma exhibited less fibrosis of lung tissues after treatment of human anti-VCAM-1 mAb." (PMID 23855490, 2013). "IV treatment with human anti-VCAM-1 mAb reduced allergic inflammation in BAL fluid, invasively measured AHR, inflammatory cell infiltration and goblet cell hyperplasia in the lung tissues of OVA-induced mouse models of acute and chronic asthma." (PMID 23855490, 2013). "Here, we believe that the induction of chronic asthma model in rats in a 70-day period led to significant pathological outcomes which is supported by the up-regulation of vascular adhesion molecules like ICAM-1 and VCAM-1 involved in cell orientation from blood into the lung parenchyma." (PMID 35209844, 2022).
chronic myelogenous leukaemia (2 papers, 2020 to 2021). "Furthermore, an exosome-mediated enhanced expression of intercellular adhesion molecule 1 (ICAM-1) and vascular cell adhesion molecule 1 (VCAM-1) in human endothelial cells have been described in a model for chronic myelogenous leukemia." (PMID 32998758, 2020). "Neo-angiogenesis also can be due to hyper-expression of vascular cell adhesion molecule-1 (VCAM-1) and intercellular adhesion molecule-1 (ICAM-1) largely found in endothelial cells treated with exosomes released from chronic myelogenous leukaemia (CML) cells." (PMID 33669294, 2021).
colon adenocarcinoma (2 papers, 2013 to 2019). "For instance, tumor interstitial fluid from colon adenocarcinoma increases the cell-surface expression levels of ICAM-1 and VCAM-1 in HUVEC cells, and tumor-derived angiogenic factors such as VEGF modulate the expression of such adhesion molecules." (PMID 24376728, 2013).
colorectal tumour (2 papers, 1998 to 2025). "In particular, the localised expression of VCAM-1 to areas of inflammation can be exploited to achieve specific visualisation of colitic lesions and colorectal tumours by labelling the peripheral activated vasculature associated with these disease sites." (PMID 40095109, 2025). "During CRC, VCAM-1 expression is upregulated both on colorectal tumour cells and endothelial cells of the surrounding microvasculature, therefore playing several distinct functions in cancer development." (PMID 40095109, 2025). "In validating the functional role of VCAM-1 in colorectal tumour development and metastasis, VCAM-1-directed therapeutics have been revealed as a potential therapeutic strategy for treating and preventing CRC." (PMID 40095109, 2025). "The upregulation of VCAM-1 on inflamed colonic vessels and colorectal tumour vasculature, coupled with its involvement in immune cell infiltration and cancer cell metastasis, has highlighted it as an attractive candidate for receptor-mediated imaging and drug delivery systems in colorectal disease." (PMID 40095109, 2025). "VCAM-1-based visualisation is yet to be explored in the context of CRC, but the promise of anti-VCAM-1 antibodies and VCAM-1-conjugated systems in other cancer models implies the likelihood of favourable outcomes for colorectal tumour visualisation." (PMID 40095109, 2025).
Crohn disease (2 papers, 2013 to 2020). A gastrointestinal disorder characterized by chronic inflammation involving all layers of the intestinal wall, noncaseating granulomas affecting the intestinal wall and regional lymph nodes, and transmural fibrosis. "Importantly, 4 of these candidate genes are key in pathways relevant in the context of human Crohn’s disease (FcgR1, Vav3, Vcam1 and Ctss), a disease with highly similar pathology to both the IL10 deficient and T. muris models of colonic inflammation." (PMID 23442222, 2013).
dry eye (2 papers, 2017 to 2018). "Long-term dry eye is associated with increased expression of inflammatory factors, such as TNF-α, MMP-2, MMP-9, ICAM-1, and VCAM-1, on the ocular surface." (PMID 30002412, 2018). "Long-term dry eye is associated with increased expression of inflammatory factors, such as tumor necrosis factor-alpha (TNF-α), matrix metalloproteinase (MMP-2, MMP-9), intercellular adhesion molecule-1 (ICAM-1), and vascular cell adhesion molecule-1 (VCAM-1) in the ocular surface." (PMID 30002412, 2018).
Duchenne muscular dystrophy (2 papers, 2018 to 2023). Duchenne muscular dystrophy (DMD) is a neuromuscular disease characterized by rapidly progressive muscle weakness and wasting due to degeneration of skeletal, smooth and cardiac muscle. "Here we report the identification of FAP subpopulations, based on Tie2 and Vcam1 expression, that reflect a continuum of cell states in dynamic transition during post-natal myogenesis, muscle repair and disease—the mdx mouse model of Duchenne Muscular Dystrophy (DMD)." (PMID 30202063, 2018). "Under further experimental measurements, the diaphragms of the duchenne muscular dystrophy (DMD) mouse model displayed a substantial decrease in the number of Tie2high subFAPs and an increase in the fraction of Vcam1+ subFAPs." (PMID 36768592, 2023). "Different patterns of Vcam1-negative Tie2high or Tie2low and Tie2low/Vcam1-expressing FAPs are detected during neonatal myogenesis, response to acute injury and Duchenne Muscular Dystrophy (DMD)." (PMID 30202063, 2018).
ductal breast carcinoma (2 papers, 2007 to 2013). "For example, more intense infiltration of malignant lesions by lymphocytes was observed in specimens of medullary breast carcinoma displaying elevated expression of CD54 (ICAM-1) and CD106 (VCAM-1) as compared with ductal breast carcinoma displaying diminished expression of these CAMs." (PMID 17325703, 2007). "Despite the low expression of BCL-6 in ductal carcinomas, the relative expression of two BCL-6 target genes, VCAM-1 and MCP-1, was not significantly elevated in tumor samples." (PMID 23737761, 2013).
E. coli infection (2 papers, 2016 to 2024). "These evidences indicate that ICAM-1 and VCAM-1 upregulation induced by meningitic E. coli infection depends on the activation of Egr-1." (PMID 38233877, 2024). "It has been shown that endothelial surface expression of ICAM-1 and CD44 is significantly elevated upon E. coli infection but expression of ICAM-2, VCAM-1 or E-selectin in pulmonary endothelial cells is not affected." (PMID 27657497, 2016).
edema (2 papers, 2013 to 2019). An abnormal accumulation of fluid beneath the skin, or in one or more cavities of the body. "In vivo, pulmonary inflammation, pulmonary edema, ultrastructure changes of type II alveolar epithelial cells, MPO activity, total cells, neutrophils, macrophages, TNF-α, IL-6 and IL-1β in BALF, along with the expression of VCAM-1 and VEGF were dose-dependently attenuated by andrographolide." (PMID 23437127, 2013).
endophthalmitis (2 papers, 2025). An infectious process affecting the internal structures of the eye. "The observed elevated levels of adhesion molecules ICAM-1 and VCAM-1 during endophthalmitis corroborate with prior studies, indicating their role in retinal inflammation." (PMID 40512033, 2025). "In the HVIP1 vitreous, there were a number of significant correlations identified: CRP/Myoglobin, IGFBP-4/SAA, IGFBP-4/VCAM-1, and VCAM-1/SAA in the endophthalmitis group; MPO/NGAL, CRP/SAA, and Cystatin C/Myoglobin in controls; and NGAL/MMP-9 in both groups." (PMID 40563988, 2025).
Fever (2 papers, 2017 to 2025). Body temperature elevated above the normal range. "Results showed that the levels of candidate proteins including HSP90α, VCAM1, PSMA1, and NID1 were higher in the fever stage of SFTS patients compared with healthy controls, almost reaching plateaus in the MOD stage, and the concentrations were decreased in the convalescent stage." (PMID 39973934, 2025).
glomerular diseases (2 papers, 2016 to 2023). "Since glomerular influx of immune cells plays a critical role in the development of some glomerular diseases, the mRNA expression of endothelial leukocyte adhesion molecules ICAM-1 and VCAM-1 in the renal cortex was measured." (PMID 37475889, 2023).
Glucose intolerance (2 papers, 2018 to 2022). Glucose intolerance (GI) can be defined as dysglycemia that comprises both prediabetes and diabetes. "Changes in cholesterol levels due to glucose intolerance induce dysregulation of ICAM-1 and VCAM-1." (PMID 36297290, 2022).
gout (2 papers, 2020 to 2025). A condition characterized by painful swelling of the joints, which is caused by deposition of urate crystals. "A pronounced upregulation of ICAM‐1 and VCAM‐1 were observed in the gout‐afflicted paws in contrast to the normal paw." (PMID 39717013, 2025). "To corroborate the in vivo binding mechanism of MLT‐MLP, we undertook a comparative analysis of MLT‐MLP localization and the expression levels of ICAM‐1 and VCAM‐1 in both healthy and gout mice." (PMID 39717013, 2025). "Subsequently, the enhanced accumulation of MLT‐MLP at gout‐afflicted sites, accompanied by the upregulated expression of ICAM‐1 and VCAM‐1 within the affected region, further corroborated our hypothesis." (PMID 39717013, 2025).
Granuloma (2 papers, 2008 to 2023). A compact, organized collection of mature mononuclear phagocytes, which may be but is not necessarily accompanied by accessory features such as necrosis. "By performing immunostaining on the STm-infected spleens, we found that VCAM-1+ granuloma MΦs are spatially localized to the periphery of granulomas." (PMID 36608122, 2023). "In contrast to blockade commenced prior to infection, this delayed blockade failed to have any effect on parasite burden, the formation of granulomas, or numbers of hepatic mononuclear cells (MNC), indicating that VCAM-1/VLA-4 interactions played no role in leukocyte recruitment to the liver." (PMID 18802456, 2008).
Headache (2 papers, 2021 to 2022). Cephalgia, or pain sensed in various parts of the head, not confined to the area of distribution of any nerve. "These FAs also inhibit macrophage activity and decrease the VCAM-1 levels resulted in attenuating severity of migraine headaches." (PMID 34301320, 2021). "The primary outcomes included headache severity, headache frequency per month, and duration of attacks and the secondary outcomes included lactate (a marker of mitochondrial function), NO, and VCAM-1 serum levels were measured at baseline and the end of the intervention." (PMID 34997178, 2022).
Hodgkin's disease (2 papers, 2021 to 2023). "Using a mouse model of Hodgkin’s lymphoma, antibody-directed targeting of tTF to VCAM-1 obliterated some vessels, reducing mean tumor volume by 45% after 3 weeks, but was not enough to entirely kill the tumors." (PMID 34356840, 2021).
hyperhomocysteinemia (2 papers, 2013 to 2025). A serious metabolic condition caused by mutations in the MTHFR gene, medications, or nutritional deficiency. "In experimental models, hyperhomocysteinemia has been associated with increased expression of vascular cell adhesion molecule-1 (VCAM-1), promoting leukocyte adhesion and perpetuating vascular inflammation and plaque progression." (PMID 40981125, 2025).
hyperthyroidism (2 papers, 2020 to 2021). Overactivity of the thyroid gland resulting in overproduction of thyroid hormone and increased metabolic rate. "In the present study, high circulating VCAM-1 levels had a synergistic effect with hyperthyroidism on low ABI values." (PMID 33051540, 2020). "Our main findings are that a lower ABI was observed in patients with hyperthyroidism and high circulating VCAM-1 levels." (PMID 33051540, 2020). "ABI was significantly lower in patients with hyperthyroidism and a high VCAM-1 level than in those with euthyroidism and a low VCAM-1 level (regression coefficient: − 0.050, 95% confidence interval [CI] between − 0.080 and − 0.019; P = 0.001)." (PMID 33051540, 2020). "Therefore, VCAM-1 might be a mediator in the relationship between hyperthyroidism and PAD." (PMID 33051540, 2020).
ileitis (2 papers, 2019 to 2024). "For instance, the study conducted by Sans and Soriano stresses the significance of blocking VCAM-1 to decrease leukocyte adhesion in rat ileitis and alleviate the inflammatory reaction in IBD." (PMID 38660311, 2024).
Impaired glucose tolerance (2 papers, 2009 to 2019). An abnormal resistance to glucose, i.e., a reduction in the ability to maintain glucose levels in the blood stream within normal limits following oral or intravenous administration of glucose. "This is surprising since, although metformin did not decrease circulating levels of C reactive protein and cell adhesion molecules in subjects with impaired glucose tolerance, it reduced the TNFα-induced activation of NFκB and secretion of VCAM-1 and MCP-1 in vascular endothelial cells." (PMID 19317897, 2009).
intrauterine growth restriction (2 papers, 2021 to 2022). "Levels of ICAM-1, VCAM-1, and E-selectin were significantly higher in women with preeclampsia and IUGR (intrauterine growth restriction)." (PMID 34065912, 2021).